PNPLA3 (patatin like domain 3, 1-acylglycerol-3-phosphate O-acyltransferase )
Diseases named in the same sentence as PNPLA3 in open-access papers (continued):
Sharing a sentence is not in itself a finding about the gene and the disease.
Hepatic steatosis (continued). "The first evidence of PNPLA3 being associated with fatty liver disease was revealed by a genome-wide association study (GWAS) of Hispanic, African American, and European American individuals in the Dallas Heart Study back in 2008." (PMID 31921875, 2019). "Italian researchers demonstrated recently that patients with inflammatory bowel disease (IBD) carrying the PNPLA3 "M" allele are at increased risk of developing hepatic steatosis and increased liver enzymes." (PMID 30161167, 2018). "The PNPLA3 "M" variant has been associated with increased hepatic steatosis and fibrosis in patients with viral hepatitis (both HCV and HBV), non-alcoholic fatty liver disease (NAFLD) and alcoholic liver disease (ALD)." (PMID 30161167, 2018). "PNPLA3 is associated with fatty liver disease and encodes a protein known to be involved in liver fat storage." (PMID 29527417, 2018). "With respect to the association of polymorphisms, PNPLA3 rs1010023 and rs738409 shared the susceptibility to hepatic steatosis in our experiments." (PMID 28695131, 2017). "The genetic polymorphism I148M of the patatin-like phospholipase domain-containing 3 (PNPLA3) is associated with hepatic steatosis and its progression to steatohepatitis (NASH), fibrosis and cancer." (PMID 29116096, 2017). "A significant association between hepatic steatosis and PNPLA3 rs1010023 was further confirmed after adjusting for age, gender, and BMI (OR = 1.77, 95% CI: 1.03–3.11; P = 0.045)." (PMID 28695131, 2017). "They observed that the PNPLA3 genetic variant was more strongly associated with severity of hepatic steatosis among those reporting drinking SSB at least once weekly compared to less frequent consumption (p = 0.03)." (PMID 29375475, 2017). "In opinion to the risk of hepatic steatosis, an intimate association of PNPLA3 SNPs (rs1010023, rs738409) was revealed with statistical significance (P = 2.18 × 10−26)." (PMID 28695131, 2017). "In the present study, C-allele of a novel PNPLA3 polymorphism, rs1010023, was uncovered to significantly associate with the susceptibility to hepatic steatosis in chronic hepatitis B patients from Southern, Central, and Northern China." (PMID 28695131, 2017). "Except for rs738409, some other PNPLA3 SNPs (rs2281135, rs139051, and rs2294918) also relate to increased risk of hepatic steatosis in ethnic groups of African, Caucasian, East Asian, and Mexican Americans." (PMID 28695131, 2017). "Our additional analysis reinforced the finding that the carriers of the rs847309 polymorphism genotype GG of the PNPLA3 gene are at increased risk of developing hepatic steatosis." (PMID 29258449, 2017). "A recent study on 62 patients with elevated liver aminotransferases reported the PNPLA3 polymorphism to be a risk factor for hepatic steatosis in HIV-infected individuals." (PMID 28594920, 2017). "Associations between the rs738409 polymorphism of the PNPLA3 gene genotype GG and hepatic steatosis and advanced fibrosis were observed." (PMID 29258449, 2017). "Genotyping for PNPLA3 polymorphisms, the C-allele at rs1010023 (CC and TC genotypes) was associated with hepatic steatosis in CHB patients (odds ratio (OR) = 1.78, 95% confidence interval (CI): 1.05–3.03; P = 0.03)." (PMID 28695131, 2017). "Single-nucleotide polymorphisms (SNPs) in patatin-like phospholipase domain-containing protein 3 (PNPLA3), which encodes adiponutrin in hepatocytes, has recently been proposed to confer the genetic susceptibility of hepatic steatosis." (PMID 28695131, 2017). "The PNPLA3 I148M variant is key risk factor for development of hepatic steatosis and its progression to more severe liver disease, with development of more advanced fibrosis, cirrhosis and cancer." (PMID 29116096, 2017). "PNPLA3 rs1010023 predisposes chronic hepatitis B patients to hepatic steatosis in the Chinese Han population." (PMID 28695131, 2017).
Hepatic steatosis (continued). "PNPLA3 polymorphisms serve as the genetic basis of hepatic steatosis in normal population and lead to dysregulated glucose metabolism." (PMID 28695131, 2017). "Associations between the rs738409 polymorphism PNPLA3 gene genotype GG and hepatic steatosis and advanced fibrosis were observed among Brazilian patients with chronic HCV." (PMID 29258449, 2017). "A recent meta-analysis revealed that the genotype PNPLA3 rs738409 GG is associated with a higher risk of hepatic steatosis (HS) in Caucasian patients with chronic hepatitis C (CHC)." (PMID 28797039, 2017). "Missense mutation (I148M) in PNPLA3 leads to a loss of function and thus promotes hepatic steatosis by limiting triglyceride hydrolysis." (PMID 27532011, 2016). "Further studies have also shown PNPLA3 rs738409 to be associated with greater hepatic steatosis and disease severity, as well as earlier clinical presentation." (PMID 27314342, 2016). "The rs58542926 (A- > G) E167K polymorphism in TM6SF2 is associated with increased steatosis in persons with chronic HCV infection, albeit to a lesser extent than the PNPLA3 polymorphism, and increased hepatic steatosis, steatohepatitis, and fibrosis in NAFLD." (PMID 28883965, 2016). "In conclusion, we demonstrated that the PNPLA3 genetic variants determined the risk of development of hepatic steatosis in Asian CHC patients." (PMID 26139292, 2015). "Taken collectively, the impact of PNPLA3 genetic variants on liver steatosis in Asian CHC patients with different characteristics has never been studied." (PMID 26139292, 2015). "This PNPLA3 gene polymorphism has also been reported to be associated with hepatic steatosis, fibrosis, treatment response, and carcinogenesis with CHC." (PMID 25713769, 2015). "PNPLA3 polymorphisms have been reported to be associated with hepatic steatosis, inflammation, fibrosis, and carcinogenesis in NAFLD." (PMID 25713769, 2015). "Because BMI and PNPLA3 genetic variants are both important determinants of hepatic steatosis, we further explored the influence of the PNPLA3 SNP in steatosis among patients with different BMIs." (PMID 26139292, 2015). "We herein recruited a large CHC cohort with histologically proven steatosis and well-characterized demographics, and we aimed to determine the association of PNPLA3 genetic variants with hepatic steatosis in an Asian CHC population." (PMID 26139292, 2015). "For patients with BMI < 24 kg/m2, the carriage of the PNPLA3 rs738409 GG genotype increased the risk of hepatic steatosis 3.4-fold when compared to those individuals carrying the C allele." (PMID 26139292, 2015). "PNPLA3 genetic variants had minimal effects on hepatic steatosis among overweight or obese patients." (PMID 26139292, 2015). "CHC patents who carried the PNPLA3 rs738409 GG genotype had a 2.3-fold risk of developing hepatic steatosis when compared to their counterparts." (PMID 26139292, 2015). "We confirmed that the PNPLA3 genetic variants consistently play a role in hepatic steatosis in Asian patients with HCV-1 and HCV-2 infections." (PMID 26139292, 2015). "If the variable of TG was taken into account, the strongest factor associated with liver steatosis remains the carriage of PNPLA3 rs738409 GG genotype (OR/CI: 2.37/1.408-3.983, P = 0.001)." (PMID 26139292, 2015). "The influence of patatin-like phospholipase domain-containing 3 (PNPLA3) genetic variants in the development of liver steatosis in Asian chronic hepatitis C patients remains elusive." (PMID 26139292, 2015). "Our results demonstrate that hepatic injury, as reflected by increased serum transaminases, is present in young children carrying the rare PNPLA3 variant already before fatty liver can be detected." (PMID 26346943, 2015). "Among the patients with normal body weights, hepatic steatosis was associated with a higher r-GT level, a lower proportion of HBsAg seropositivity and a higher proportion of PNPLA3 rs738409 G genotype carriage in univariate analysis." (PMID 26139292, 2015).
Hepatic steatosis (continued). "This was subsequently associated with ethnic variation in the prevalence of allelic variants of the patatin-like phospholipase 3 (PNPLA3) gene; with the PNPLA3 rs738409 (G) allele strongly associated with increased hepatic steatosis and inflammation." (PMID 26703719, 2015). "In the univariate analysis, the factors associated with fatty liver included older age, high body mass index (BMI), the presence of diabetes, a high r-glutamyltransferase (r-GT) level and carriage of the PNPLA3 rs738409 GG genotype, using the recessive model." (PMID 26139292, 2015). "In the current large-scale study, we demonstrated that the influence of the PNPLA3 genetic variants in hepatic steatosis remains consistent in Asian CHC populations, and the effect is independent of other metabolic disorders." (PMID 26139292, 2015). "In conclusions, both PNPLA3 genetic variants and BMI played important roles in hepatic steatosis among Asian chronic hepatitis C patients." (PMID 26139292, 2015). "PNPLA3 polymorphisms have also been reported to be associated with hepatic steatosis, fibrosis, treatment response, and carcinogenesis in CHC." (PMID 25713769, 2015). "Overexpression of the PNPLA3 I148M polymorphism in mice also causes hepatic steatosis and PNPLA3 has been shown to regulate hepatic lipid metabolism." (PMID 25617409, 2015). "Nevertheless, we demonstrated the associations between the PNPLA3 SNP and other simple demographic characteristics with hepatic steatosis." (PMID 26139292, 2015). "It had been reported that PNPLA3 rs738409 was associated with hepatic steatosis and steatohepatitis in NAFLD." (PMID 24349054, 2013). "Genome-wide array studies have associated the patatin-like phospholipase domain-containing 3 (PNPLA3) gene polymorphisms with hepatic steatosis." (PMID 23175050, 2013). "Surprisingly, genes fundamental to lipid metabolism, including Scd1, Fasn, Elovl6, and Pnpla3-implicated in Fatty Liver Disease pathogenesis, were predominant in females." (PMID 23977068, 2013). "PNPLA3 polymorphism primitively predisposes to liver steatosis which in turn activates the cascade of events leading to liver inflammation." (PMID 22927922, 2012). "A single genetic variant, PNPLA3 I148M, has been widely associated with increased hepatic steatosis." (PMID 22978414, 2012). "The most widely replicated genetic variant associated with hepatic steatosis is an isoleucine to methionine substitution at position 148 (I148M, rs738409) in the patatin-like phospholipase domain-containing 3 gene (PNPLA3)." (PMID 22724004, 2012). "DGAT catalyses the committed step in triacylglycerol synthesis with DGAT2 being the dominant DGAT enzyme controlling triacylglycerol homeostasis in vivo, and PNPLA3 has been implicated in the development of hepatic steatosis." (PMID 22974251, 2012). "PNPLA3 I148M is the most widely replicated genetic variant associated with increased hepatic steatosis." (PMID 22978414, 2012). "A single nucleotide polymorphism (SNP), the rs738409, in the patatin like phospholipase 3 gene (PNPLA3) has been recently associated with increased hepatic steatosis and ALT levels in adults and children." (PMID 22629460, 2012). "Recently, two genome wide association studies identified a polymorphism in PNPLA3 gene, rs738409 C>G, encoding for the I148M protein variant, as the strongest genetic determinant of hepatic steatosis and increased ALT levels." (PMID 23226254, 2012). "Previous studies showed association between PNPLA3 and fatty liver, inflammation, fibrosis grade and NASH." (PMID 22719876, 2012). "Two loci, NFKBIB and RELA, are involved in NFKB signaling pathway; PNPLA3 is known for its association with fatty liver disease; and SH3B2 has been associated with a multitude of traits and disease including myocardial infarction." (PMID 21533024, 2011). "The accumulation of PNPLA3 on hepatic lipid droplets is the basis of associated hepatic steatosis." (PMID 40507973, 2025).
Hepatic steatosis (continued). "In a recent study, the use of liver-targeted ASO to silence patatin-like phospholipase domain containing 3 (PNPLA3) in a knock-in mouse model with the human PNPLA3 I148M variant resulted in reduced liver steatosis, inflammation, and fibrosis, alongside decreased inflammatory markers." (PMID 40438258, 2025). "Our findings suggest that PNPLA3 I148M might affect the liver fat distribution and could be used to predict the presence of PNPLA3 variants in patients with fatty liver." (PMID 40478199, 2025). "When looking at the interplay between the PNPLA3 rs738409 C > G variant and the occurrence of diabetes, in a large Asiatic general population after 4 years of follow‐up the PNPLA3 GG at‐risk genotype disentangles the risk of fatty liver and 2‐h oral glucose tolerance test." (PMID 39412170, 2025). "Concerning PNPLA3, it has been recently suggested that the I148M variant may be a gain-of-function mutation that promotes hepatic steatosis by accumulating lipid droplets and inhibiting other lipases in an ABHD5-dependent manner." (PMID 40563253, 2025). "Japanese Americans have been found to have larger areas of visceral and hepatic adipose tissue compared to African Americans, and it has been suggested that polymorphisms in the PNPLA3 gene may be closely associated with hepatic steatosis." (PMID 40142230, 2025). "GCKR and PNPLA3 act together to convey susceptibility to fatty liver in obese young adults." (PMID 40507973, 2025). "This may be due to genetic factors, such as the PNPLA3 mutation, which is linked to an increased risk of hepatic steatosis and NASH, particularly in Hispanics." (PMID 40004054, 2025). "Within the PNPLA3 gene, it exists in a non-synonymous SNP (rs738409 C/G), a coding variant that encodes an amino acid substitution I148M and shows a strong correlation with fatty liver disease and its histological severity in both adults and children." (PMID 40004054, 2025). "It showed that patients with PNPLA3-associated steatohepatitis show better improvement of hepatic steatosis after MBS as compared to carriers of PNPLA3 wild-type alleles; consequently, PNPLA3 rs738409 is a good prognostic factor for MASLD patients undergoing MBS." (PMID 39125390, 2024). "For example, patients with MASLD who possess a susceptibility mutation in of PNPLA3 are also more sensitive to liver steatosis mediated by dietary factors, and further studies are needed to elaborate on the association between diet and liver fibrosis in this population." (PMID 39221157, 2024). "Multiple studies have proven the presence of a genetic component that is associated with fatty liver prevalence and both Native American and Hispanic populations with high prevalences of patatin-like phospholipase domain-containing 3 (PNPLA3; rs738409 C/G, M148I) polymorphisms." (PMID 38892917, 2024). "The I148M variant of PNPLA3 is closely associated with hepatic steatosis." (PMID 38844467, 2024). "Suppression of diacylglycerol acyltransferase-2 (DGAT2), but not DGAT1, with antisense oligonucleotides reversed diet-induced hepatic steatosis and insulin resistance, suggesting that PNPLA3-mediated lipid accumulation is possibly associated with DGAT2 signaling." (PMID 39000384, 2024). "It is well known that a common mutation (I148M) in the PNPLA3 gene is highly related to liver steatosis, and findings in vitro and in mice have shown that the I148M mutation results in increased PNPLA3 binding to CGI-58 and diminished ATGL-mediated lipolysis of hepatic TG." (PMID 37591342, 2023). "However, in a study of adult Greeks, it was shown by multivariate analysis that the PNPLA3 variant rs738409, WC and female sex were directly associated with fatty liver disease, whereas the duration of DM had an inverse association." (PMID 37189715, 2023). "Finally, data from Greece referring only to the adult population support that the PNPLA3 variant plays a vital role in hepatic steatosis development in patients with type 2 diabetes." (PMID 36079710, 2022).
Hepatic steatosis (continued). "The severity of hepatic steatosis is modulated by genetic variants, such as patatin-like phospholipase domain containing 3 (PNPLA3) rs738409, transmembrane 6 superfamily member 2 (TM6SF2) rs58542926, and membrane-bound O-acyltransferase domain containing 7 (MBOAT7) rs641738." (PMID 36555467, 2022). "These contrasting findings were inconsistent with the hypothesis that PNPLA3 causes hepatic steatosis due to a simple loss or gain of function." (PMID 33926085, 2021). "The variant near or in PNPLA3 (rs738409) was significantly associated with hepatic steatosis in Hispanic Americans, and the G allele was higher in this population than in European or African American ancestry, and it was consistent with the higher prevalence of this disease in Hispanics." (PMID 34202120, 2021). "The aim of the present study was to determine whether PNPLA3 polymorphism is linked to the degree of hepatic steatosis and fibrosis in patients with HCV infection and whether PNPLA3 is related to fibrosis and steatosis evolution three monthspost-SVR." (PMID 34833371, 2021). "Alcohol excess causes hepatic steatosis, and therefore, in alcohol-related liver disease, PNPLA3-I148M may increase risk of progression through a shared mechanism with NAFLD." (PMID 33544287, 2021). "Furthermore, the association of PNPLA3 gene polymorphisms with other liver disorders such as alcoholic fatty liver (ALD) has also been observed.." (PMID 34147109, 2021). "In several liver diseases, an independent association exists between PNPLA3 and steatosis and fibrosis accumulation; additionally, PNPLA3 is associated with an elevated risk of hepatocellular carcinoma development in individuals with cirrhosis that developed from fatty liver disease." (PMID 34206460, 2021). "One of the strongest and most studied genetic risk factors for NAFLD worldwide is the single nucleotide polymorphism (SNP) rs738409 C > G in PNPLA3, which encodes the protein variant I148M, and has been associated with hepatic steatosis and fibrosis progression in children and adults." (PMID 33102800, 2020). "Second, because PNPLA3 148M protein is hypothesized to cause hepatic steatosis primarily through its toxic accumulation and sequestration of CGI-58, there are no specific enzymatic activities to be inhibited by a small molecule approach." (PMID 33036387, 2020). "They found a strong association between fatty liver and the PNPLA3 variant rs738409 C>G p.I148M, which causes a loss of function that is statistically more prevalent in the Hispanic population, thus justifying the major incidence of NAFLD reported in this population." (PMID 31010049, 2019). "Furthermore, HepG2 cells show altered lipid metabolism, and they carry the homozygous variant rs738409 of patatin-like phospholipase domain-containing protein 3 (PNPLA3) gene, the variant which is strongly associated with hepatic steatosis." (PMID 31382615, 2019). "Notably, EASL–EASD–EASO Clinical Practice Guidelines35 already suggest genotyping for TM6SF2 and PNPLA3 to select patients with higher risk of hepatic steatosis." (PMID 29487372, 2018). "In addition, the PNPLA3 I148M variant was also found to be associated with elevated serum aminotransferase levels, increased computed tomography–measured hepatic steatosis, and histologic HS." (PMID 30189691, 2018). "This hypothesis is also supported by the finding that PNPLA3 E434K, a variant that decreases PNPLA3 expression, can attenuate the effect of I148M on hepatic steatosis and steatohepatitis." (PMID 30355853, 2018). "It is well known that the increased expression of PNPLA3 is associated with hepatic steatosis." (PMID 29749571, 2018). "They further proposed that PNPLA3(148M) causes hepatic steatosis due to a loss in this activity." (PMID 29555681, 2018). "In a sample of 200 Italian youths (10–13 years) at high risk for NAFLD, Nobili and colleagues examined whether PNPLA3 interacted with SSB consumption to influence the severity of hepatic steatosis." (PMID 29375475, 2017).